ARL4C (ARF like GTPase 4C)
Diseases named in the same sentence as ARL4C in open-access papers (continued):
Sharing a sentence is not in itself a finding about the gene and the disease.
breast cancer (2 papers, 2022 to 2023). A primary or metastatic malignant neoplasm involving the breast. "Specifically, ARL4C expression was lower in ACC, breast cancer (BRCA), KICH, prostate adenocarcinoma (PRAD), skin cutaneous melanoma (SKCM), and thyroid carcinoma (THCA) compared to normal tissues." (PMID 38178862, 2023). "IPA showed that the pathways of mammary tumours, genitourinary tumours and extracranial solid tumours were strongly activated in G1 cells, in which AREG, ARL4C, and ARID5B showed the greatest contribution to activation." (PMID 35184420, 2022).
cervical carcinoma (2 papers, 2016 to 2024). A carcinoma arising from either the exocervical squamous epithelium or the endocervical glandular epithelium. "As compared to the level of ARL4C mRNA expression in HeLaS3 cervical cancer cells, ARL4C mRNA was highly expressed in NCI-H520 lung SCC cells and SAS tongue SCC cells." (PMID 27835592, 2016). "It has been shown previously that the level of ARL4C in cultured human cervical carcinoma (HeLa) cells could be increased through the activation of the liver X receptor (LXR) and retinoid X-receptor (RXR) or cholesterol loading." (PMID 39767779, 2024). "We showed for the first time that the elevation of the endogenous ARL4C level through the RXR/LXR-dependent pathway in human cervical carcinoma HeLa cells is accompanied by an increased non-centrosomal nucleation of microtubules." (PMID 39767779, 2024).
cervical squamous cell carcinoma (2 papers, 2022 to 2023). A squamous cell carcinoma arising from the cervical epithelium. "Notably, ARL4C exhibited a positive correlation with CNV in several tumors, including OV, cervical squamous cell carcinoma and endocervical adenocarcinoma (CESC), and KICH." (PMID 38178862, 2023).
liver cancer (2 papers, 2023 to 2025). An epithelial or non-epithelial malignant neoplasm that arises from the liver. "Our findings reveal a notable association between ARL4C expression and CTL dysfunction in breast, endometrial, and liver cancer (p = 0.0177, p = 0.0149, p = 0.0226)." (PMID 38178862, 2023).
osteosarcoma (2 papers, 2023 to 2024). A usually aggressive malignant bone-forming mesenchymal neoplasm, predominantly affecting adolescents and young adults. "We checked the possibility of activating this pathway and changing the level of endogenous ARL4C in another widely used African green monkey kidney cells (COS7) and human cancer U2OS osteosarcoma cell line." (PMID 39767779, 2024).
sarcoma (2 papers, 2022 to 2023). A usually aggressive malignant neoplasm of the soft tissue or bone. "Notably, high ARL4C expression demonstrated positive associations with immune pathways across plenty of tumors, including KICH, PRAD, THCA, rectum adenocarcinoma (READ), lymphoid neoplasm diffuse large B-cell lymphoma (DLBC), sarcoma (SARC), BRCA, and BLCA, among others." (PMID 38178862, 2023).
adrenocortical carcinoma (1 paper, 2023). "Conversely, ARL4C expression was found to be lowest in adrenocortical carcinoma (ACC), kidney chromophobe (KICH), and uveal melanoma (UVM)." (PMID 38178862, 2023).
anaplastic gliomas (1 paper, 2021). "Furthermore, ARL4C expression in Grade IV GBM was higher than that in Grade III anaplastic gliomas (P < 0.05)." (PMID 33403039, 2021).
basal cell carcinoma (1 paper, 2023). A carcinoma involving the basal cells. "In the BCC_GSE123813 dataset, ARL4C exhibited widespread expression on immune cells such as DC cells, monocytes, and macrophages within the TME of basal cell carcinoma (BCC)." (PMID 38178862, 2023).
bone metastasis (1 paper, 2026). Transfer of a neoplasm from its primary site to bones. "Moreover, in four representative cases exhibiting distant metastases—liver metastasis at 6 months, pulmonary metastasis at 11 months, bone metastasis at 17 months, and brain metastasis at 26 months post-surgery—ARL4C levels were markedly elevated." (PMID 41328352, 2026).
ependymoma (1 paper, 2023). A WHO grade II, slow growing tumor of children and young adults, usually located intraventricularly. "ARL4C transcription is significantly upregulated (p-value: 1.63e−16) in PFA tumors compared to other ependymoma groups and is highly correlated with the activity of the enhancer elements that physically interact with the ARL4C gene locus in PFA but not in ZFTA tumors." (PMID 37085539, 2023).
kidney cancer (1 paper, 2023). Primary or metastatic malignant neoplasm involving the kidney. "Consistent with the bioinformatical analysis, the expression level of ARL4C was found to be higher in various types of cancer tissues (LIHC, kidney cancer, and COAD) compared to healthy tissues." (PMID 38178862, 2023).
metastatic colorectal cancer (1 paper, 2021). "ARL4C has been reported to be highly expressed in metastatic colorectal cancer and is associated with poor prognosis." (PMID 33959617, 2021).
mucinous adenocarcinoma (1 paper, 2026). An invasive adenocarcinoma composed of malignant glandular cells which contain intracytoplasmic mucin. "Moreover, ARL4C levels were markedly higher in mucinous adenocarcinomas, characterized by a higher degree of malignancy, compared with conventional adenocarcinomas and adjacent tissues." (PMID 41328352, 2026). "Notably, higher ARL4C levels were observed in aggressive subtypes, such as mucinous adenocarcinoma." (PMID 41328352, 2026).
Obesity (1 paper, 2022). Accumulation of substantial excess body fat. "Overall, these data suggest that ARL4C methylation may be a promising obesity-related epigenetic marker." (PMID 36528638, 2022).
pancreatic adenocarcinoma (1 paper, 2021). "(C) ARL4C mRNA levels in pancreatic adenocarcinoma and normal pancreatic tissues were analyzed using TCGA and GTEx datasets." (PMID 34590580, 2021).
Sepsis (1 paper, 2024). Sepsis is defined as life-threatening organ dysfunction caused by a dysregulated host response to infection. "Furthermore, ARL4C knockdown in sepsis model in vivo and vitro caused increased inflammatory response and a worse prognosis." (PMID 38404591, 2024). "The ARL4C knockdown group showed increased LPS-induced apoptosis and ROS production rates, suggesting that ARL4C blocking may make macrophages more susceptible to apoptosis and enhance the excessive inflammatory response during sepsis." (PMID 38404591, 2024). "In this section, we further substantiate the role of characteristic genes, particularly ARL4C, in sepsis and demonstrate its protective function by attenuating excessive inflammation." (PMID 38404591, 2024). "To corroborate this notion, we created a knock-down model and discerned that an enhanced immune-inflammatory response corresponded with a decrease in the expression levels of ARL4C in sepsis." (PMID 38404591, 2024). "We discovered that both CD247 and ARL4C exhibited high levels of expression in the bloodstream of the sepsis-afflicted rat, potentially serving as beneficial immune-inflammatory regulators." (PMID 38404591, 2024). "In this study, we discovered that the knockdown of ARL4C in an in vitro sepsis model potentially renders macrophages more vulnerable to apoptosis and exacerbates the inflammatory response during sepsis." (PMID 38404591, 2024). "Overall, our study is the first to identify ARL4C’s involvement in the sepsis inflammatory response by affecting DDR, suggesting its significance in maintaining an appropriate inflammatory response." (PMID 38404591, 2024). "Sepsis rats with ARL4C knock-down also exhibited a higher mortality rate." (PMID 38404591, 2024). "Moreover, survival analysis indicated that rats with reduced ARL4C expression had lower survival rates in comparison to those in both the sham and sepsis+Ad-shNC groups." (PMID 38404591, 2024). "Notably, in the Ad-shARL4C group, ARL4C expression decreased to approximately one-third of that observed in the sepsis+Ad-shNC group, validating the efficiency of gene silencing in our model." (PMID 38404591, 2024). "However, the investigation of ARL4C’s role in sepsis remains notably scarce." (PMID 38404591, 2024).
stomach adenocarcinoma (1 paper, 2023). "Specifically, ARL4C exhibited a positive correlation with BRCA and COAD, while showing a negative correlation with DLBC, SKCM, stomach adenocarcinoma (STAD), and UCEC." (PMID 38178862, 2023).
tongue cancer (1 paper, 2016). A malignant neoplasm affecting the tongue. "The current study was conducted to investigate the expression and functions of ARL4C due to DNA hypomethylation in lung and tongue cancers." (PMID 27835592, 2016).
tongue SCC (1 paper, 2016). "In summary, we found that ARL4C is overexpressed in tumor lesions of lung and tongue SCC cancers with high frequencies and that ARL4C expression is regulated by DNA methylation at the 3’-UTR through TETs." (PMID 27835592, 2016). "Immunohistochemical analyses of tissue specimens obtained from lung and tongue squamous cell carcinoma (SCC) patients revealed that ARL4C is not observed in non-tumor regions, but is strongly expressed at high frequencies in tumor lesions." (PMID 27835592, 2016).
tongue tumor (1 paper, 2016). "It is noteworthy that ARL4C was clearly detected in the invasion front of tongue tumor lesions." (PMID 27835592, 2016).
tumor (26 papers, 2016 to 2026). "TCGA analysis revealed a positive correlation between ARL4C expression and tumor mutational burden (TMB)." (PMID 41328352, 2026). "To explore potential mechanisms underlying the tumor immune microenvironment, we utilized a publicly available scRNA-seq (single-cell RNA-seq) dataset to investigate the expression of ARL4C across various immune cell types." (PMID 38178862, 2023). "Nevertheless, the precise functional mechanisms of ARL4C concerning tumor prognosis and immunotherapy drug susceptibility remain elusive." (PMID 38178862, 2023). "Furthermore, the ESTIMATE algorithm and TIMER2.0 database were utilized to analyze the tumor microenvironment and immune infiltration associated with ARL4C." (PMID 38178862, 2023). "Consequently, we conducted a bioinformatics analysis of ARL4C across multiple cancer types and investigated its underlying impact on tumor immunology." (PMID 38178862, 2023). "Furthermore, the in vivo analysis showed that silencing ARL4C in MKN45 cells caused obvious reductions in tumour weight and volume in nude mice." (PMID 33724652, 2021). "IHC analysis revealed that ARL4C expression was significantly elevated in resistant patients and strongly correlated with tumor grade, stage, recurrence, and metastasis." (PMID 41328352, 2026). "Functionally, β-Lapachone in combination with oxaliplatin robustly suppressed tumor metastasis, comparable to ARL4C knockdown plus oxaliplatin." (PMID 41328352, 2026). "Functional assays demonstrated that ARL4C knockdown sensitized CRC cells to oxaliplatin and promoted apoptosis, whereas ARL4C overexpression accelerated tumor growth and impaired chemotherapy response in vivo." (PMID 41328352, 2026). "Subcutaneous tumor and metastasis models confirmed that ARL4C overexpression significantly increased metastatic nodules in the lungs and liver, while ARL4C silencing nearly abolished metastasis formation." (PMID 41328352, 2026). "Pan-cancer analyses revealed that ARL4C is significantly overexpressed in 23 tumor types, including CRC, compared with normal tissues." (PMID 41328352, 2026). "ARL4C promotes tumor survival and migration through the RAP1/PI3K-Akt/mTOR signaling loop and the RAC1/EMT signaling axis, and sustains its expression via deubiquitinase-mediated stabilization, thereby forming a positive feedback loop." (PMID 41328352, 2026). "Given its integrative roles in signaling regulation, functional driving of tumor progression, and amenability to structural targeting, ARL4C represents a promising therapeutic vulnerability." (PMID 41328352, 2026). "ARL4C regulates both tumor cell survival and metastatic capacity, making it an ideal therapeutic target." (PMID 41328352, 2026). "Tumor samples from this patient exhibited substantially higher ARL4C expression compared to other cases with either isolated recurrence or single-site metastasis." (PMID 41328352, 2026). "ARL4C is known to be upregulated across multiple tumor types and promotes proliferation and migration via pathways, such as the Wnt/β-catenin pathway." (PMID 41328352, 2026). "Targeting PTEN potently inhibited GBM tumor progression in vitro and in vivo, whereas overexpression of ARL4C reversed the tumor progression impaired by PTEN overexpression." (PMID 39767779, 2024). "Validation through multiple Immunohistochemistry (mIHC) confirms the prominence of ARL4C, ARPC1B, and TERF2IP in tumor tissue, and their expression were negatively associated with CD8 T cell presence." (PMID 38419085, 2024). "Various studies suggest that ARL4C plays a crucial role in intensifying tumor proliferation, invasion, and drug resistance via immune-related pathways, which include Wnt/β-catenin, AKT/mTOR, and MEK/ERK." (PMID 38404591, 2024). "Immunofluorescence staining of tumor and normal tissue specimens further confirmed a positive correlation between ARL4C and TAMs and CAFs, suggesting a close relationship between ARL4C and immune infiltration in tumor cells." (PMID 38178862, 2023).
tumor (continued). "A strong correlation exists between ARL4C and immune score across 22 tumor samples (p < 0.05), with positive correlations observed in 21 tumors, except for a negative correlation with the immune score of OV." (PMID 38178862, 2023). "Fortunately, our findings confirmed the involvement of ARL4C in the tumor immune microenvironment, thereby expanding the potential of ARL4C-targeted tumor immunotherapy." (PMID 38178862, 2023). "In vitro experiments, we investigated the expression levels of ARL4C in four tumor cell lines treated with various cytokines, namely IFNβ, IFNγ, TGFβ, and TNFα." (PMID 38178862, 2023). "The results revealed significant disparities in ARL4C expression within the IFNβ and IFNγ-treated tumor cell lines." (PMID 38178862, 2023). "Our results revealed a significant correlation between the expression of ARL4C and stromal scores among 28 tumors (p < 0.05), with a positive correlation observed in 27 tumor types." (PMID 38178862, 2023). "Recognizing the significance of copy number variation (CNV) in tumor development, we further examined the relationship between ARL4C and CNV in the 33 tumors." (PMID 38178862, 2023). "Immunohistochemistry and immunofluorescence staining techniques were utilized to confirm the expression of ARL4C in particular tumor tissues." (PMID 38178862, 2023). "In cancer stromal cells, ARL4C expression was significantly stronger in cases with high-grade tumor budding than in cases with low-grade tumor budding (P = 0.0002)." (PMID 37237373, 2023). "ARL4C assumes crucial functions in the realm of tumor cell biology, encompassing stem cell-like attributes, proliferation, and resistance to pharmaceutical agents." (PMID 38178862, 2023). "Our evaluation revealed a statistically significant increase in ARL4C mRNA expression in 23 different tumor tissues compared to normal tissue." (PMID 38178862, 2023). "ARL4C assumes critical functions in the biology of tumor cells, encompassing stem cell-like characteristics, proliferation, and resistance to therapeutic agents." (PMID 38178862, 2023). "Based on our preliminary findings, there was a notable variance in ARL4C expression between malignant cells and macrophages within certain tumor types, such as the BCC immunotherapy cohort, when comparing the treated cohorts to their untreated counterparts." (PMID 38178862, 2023). "Many previous studies confirmed that ARL4C is involved in the formation and progression of various cancers, and the functions and molecular mechanisms of ARL4C differ significantly according to the tumor type." (PMID 35774359, 2022). "We also found that the level of ARL4C and patient tumor grade together correlated with the prognosis of patients (P < 0.0001)." (PMID 35774359, 2022). "The results indicated that the protein expression of ARL4C in the tumour tissues was significantly higher than that in the adjacent mucosa tissues." (PMID 33724652, 2021). "ARL4C expression was considered high when the total area of the tumor stained with anti-ARL4C antibody exceeded 5 %." (PMID 34590580, 2021). "ARL4C staining in the tumor lesions was calculated as a continuous variable, and the patients were classified into two groups (high and low), depending on ARL4C expression levels." (PMID 34590580, 2021). "High expression of ARL4C was observed in 47 cases (82%), but minimally detected in non-tumor regions of pancreatic ducts." (PMID 34590580, 2021). "GSLCs, determined by the efficiency of sphere formation in vitro and tumor growth in vivo, was increased by overexpression of ARL4C." (PMID 33403039, 2021). "When 6-FAM–labeled ARL4C ASO-1316 was subcutaneously injected into tumor-bearing mice, the fluorescence was extremely detected in the pancreas and slightly observed in the kidney which is due to renal excretion." (PMID 34590580, 2021).